DNMT1 (DNA methyltransferase 1)
Diseases named in the same sentence as DNMT1 in open-access papers (continued):
Sharing a sentence is not in itself a finding about the gene and the disease.
tumor (continued). "More aggressive PitNETs, defined by larger size and invasiveness, have been associated with the overexpression of DNA methyltransferases 1/3A (DNMT1/3A) and promoter hypermethylation of tumor suppressor genes." (PMID 40959438, 2025). "SCFAs inhibit DNA methyltransferases (e.g., DNMT1), leading to demethylation and re-expression of tumor suppressor genes (e.g., SFRP2, WIF1), which in turn inhibit Wnt signaling and tumor growth." (PMID 41450947, 2025). "This epigenetic alteration facilitates the transcriptional activation of these genes, driving aggressive tumor behavior and underscoring DNMT1’s pivotal role in modulating epigenetic landscapes within PCa cells." (PMID 40034825, 2025). "Elevated DNMT1 then hypermethylates CpG-rich promoters of the key tumor suppressors, including CDH13, hampering their transcription and disrupting cell–cell adhesion across multiple malignancies (lung, gastric, and breast)." (PMID 40649905, 2025). "Pharmacological inhibition of DNMT1 reduced tumor growth in a cell line and in vivo mouse models of SHH-MB." (PMID 40599851, 2025). "When PI3K agonists were applied to DNMT1-silenced mice, only a modest increase in tumor growth was observed." (PMID 38755637, 2024). "DNMT1 knockout HCT116 cells exhibited decreased CSC marker expression and impaired tumor-initiating ability but a growth rate similar to that of DNMT1-WT cells, indicating the involvement of DNMT1 in CSC-specific maintenance and functionality." (PMID 38254219, 2024). "The observed reduction in the number of proliferative cells and increase in the number of apoptotic cells within the sh-DNMT1 group provided evidence of a significant tumor-suppressing effect." (PMID 38755637, 2024). "The current study unveils an intriguing discovery indicating that DNMT1 knockdown more strongly inhibits tumor growth than does inhibition of the PI3K-AKT pathway alone." (PMID 38755637, 2024). "Mice treated with combination inhibitors exhibited comparable suppression of tumor growth to mice bearing sh-DNMT1 tumors." (PMID 38755637, 2024). "Our results showed that NSUN2, DNMT1, DNMT3A, DNMT3B, TRDMT, and ALYREF were related to high or low tumor risk, while NOP2 was related to the pTNM stage of tumors." (PMID 38579085, 2024). "Remarkably, elevated acetylation levels of STAT3 within tumor tissues can bind to DNMT1, resulting in the inhibition of tumor suppressor genes via promoter CpG island methylation." (PMID 38834851, 2024). "A recent study revealed that targeting DNA methyltransferase 1 (DNMT1) programs immunologically anergic tumor vasculature, and its phosphorylation is promoted by FGF2." (PMID 37864726, 2024). "UHRF1 coordinates with DNMT1 to ensure DNA methylation during cell division, a key process for silencing tumor suppressor genes and promoting oncogenesis." (PMID 39684755, 2024). "Quantification of the global DNA methylation by pyrosequencing LINE-1 elements in the tumor genome revealed a decline of CpG methylation levels when CM-272 was present, suggesting the hindered function of DNMT1." (PMID 38285887, 2024). "Our report confirms the possibility of DNMT1/miR-152-3p/SOS1 regulating the tumor growth and self-renewal of LCSLCs, providing new insights into the initiation and progression of NSCLC." (PMID 38622665, 2024). "The proportion of Ki67-positive cells in sh-DNMT1 tumor-bearing mice was found to be mitigated, offering further evidence for the enhanced anticancer efficacy of DNMT1 silencing." (PMID 38755637, 2024). "We identified Dnmt1 as a druggable dependency in SHH-MB and show that DNMT1 inhibition can effectively inhibit tumor growth both in in vitro and in vivo models of SHH-MB by suppressing SHH signaling output." (PMID 39107797, 2024). "This discovery provides additional evidence for the existence of other mechanisms that inhibit tumor growth as a result of DNMT1-specific DNA hypomethylation." (PMID 38755637, 2024).
tumor (continued). "Intriguingly, the suppressive effect on tumor shrinkage was more prominent in cases of DNMT1 knockdown compared to PI3K inhibitor treatment." (PMID 38755637, 2024). "This research demonstrates that the DNMT1 inhibitor dihydroergotamine (compound 4) modulates a multitude of tumor progression hallmarks, such as migration, apoptosis, and cell proliferation." (PMID 39595939, 2024). "Studies have proposed that statins play a role in modifying the DNA methylation profile by downregulating DNMT1, thereby altering the transcription profile toward a tumor suppressive phenotype." (PMID 38711272, 2024). "set-up tumor context-specific conditions for therapeutic intervention via DNMT1 inhibitors to avoid unwanted toxicity." (PMID 39056791, 2024). "The tumour tissues were homogenized to extract protein, and 15a downregulated the expression of DNMT1 and HDAC1, increased the acetylation of H3, and upregulated the expression of the apoptosis-related protein caspase-3 and the cell cycle-related protein p27." (PMID 38490978, 2024). "Overall, augmentation of TET2 and activation of tumor suppressors had minimal effects on altering the resistance to DNMTi conferred by DNMT1 gene deletion." (PMID 39057134, 2024). "The results indicate that the DNMT1/miR-152-3p pathway promotes the self-renewal and tumor growth of A549-derived LCSLCs through the regulation of SOS1 expression." (PMID 38622665, 2024). "For instance, DNA methyltransferase 1 (DNMT1) maintains tumor cell dormancy and stemness by blocking the G1/S phase transition signaling network." (PMID 38994941, 2024). "Compared to mice that received a single PI3K inhibitor, mice in which DNMT1 was silenced also exhibited the slowest tumorigenesis and superior control of tumor growth in the earlier intervention." (PMID 38755637, 2024). "Previous research has demonstrated that silences DNMT1 gene activity and leads to the activation of a number of tumor-related target genes." (PMID 38436027, 2024). "UHRF1/DNMT1-mediated DNA methylation plays a crucial role in promoting the epigenetic silencing of TSGs and facilitating tumor progression." (PMID 39267107, 2024). "In our nude mouse graft model, the knockdown of DNMT1 led to the inhibition of tumor growth, accompanied by decreased protein expression of DNMT1, SOS1, and CD44 and increased levels of miR-152-3p." (PMID 38622665, 2024). "All these processes represent a signaling synergy orchestrated by DNMT1, acting as a gatekeeper to effectively restrain tumor growth through enhancing efficiency and reducing toxicity." (PMID 38755637, 2024). "The innate immune response, which serves as a tumor suppressor, can be suppressed by the DNA methyltransferase 1 (DNMT1), which maintains the silencing of retrotransposable elements." (PMID 38736884, 2024). "Compared to PI3K inhibitors, DNMT1 targeting demonstrated superior in vivo tumor suppression, mitigating the toxic effects of blood glucose variation caused by PI3K and PI3K-CDK inhibitor combinations." (PMID 38755637, 2024). "We subsequently examined increased glycogen clustering in sh-DNMT1 tumor tissues, similar to those treated with combined inhibitors, but notably more than in tumors treated in solely with PI3K inhibitors or vehicle." (PMID 38755637, 2024). "TET2 augmentation contributed to the CDKN2A promoter demethylation, tumor suppressor re-expression, and concomitant resistance to DNMT inhibitors in the DNMT1 gene deleted state." (PMID 39057134, 2024). "Studies have shown that DNMT1 is highly expressed in the nucleus in human PCa specimens and is related to tumor stage, Gleason score, and AR expression." (PMID 36755811, 2023). "In this work, to further define the precise mechanisms underlying epigenetic modulation of anti-tumor immunity in the tumor microenvironment, we generate a conditional deletion model to disable DNMT1 activity, specifically in the endothelium." (PMID 37055433, 2023).
tumor (continued). "Next, we determined the effect of EGCG on DNA methylation and DNMT1, DNMT3a, and DNMT3b expression in tumor tissues." (PMID 36979768, 2023). "The tumor growth delay and inhibition of expression of DNMT1 and upregulation of p21 were also achieved by decitabine and aza-T-dCyd treatment in bladder PDX model." (PMID 37045940, 2023). "Combined EZH2 and DNMT1 inhibition increased effector T-cell tumor infiltration, inhibited tumor progression, and improved the therapeutic efficacy of PDL-1 blockade." (PMID 36984544, 2023). "DNA in the tumor suppressor gene promoters bound to the acetylated histone-H3 was increased in DNMT1−/− cells relative to DNMT1+/+ cells upon exposure to decitabine for 72 h." (PMID 37045940, 2023). "Inhibition of CAMK2N1 significantly enhanced the migration and invasion of PCa cells and xenograft tumor growth, while the knockdown of DNMT1 reversed these effects." (PMID 36755811, 2023). "Next, we detected the protein expression levels of NSUN4, NSUN7, and DNMT1 via IHC staining in a tissue microarray containing 80 paired normal and tumor tissues." (PMID 36911744, 2023). "By doing so, we uncover a role for DNMT1 in tumor blood vessels, including influences on tumor growth, microvessel patterning, and regulation of CAMs and chemokines that permit T-cell trafficking across the vasculature." (PMID 37055433, 2023). "MG98, which blocks the activity of DNMT1, has the potential to inhibit tumor growth and reactivate tumor suppressor genes." (PMID 36542159, 2023). "It is interesting to note that co-treatment of casticin and agomir-148a-3p showed the strongest inhibitory effect on the tumor weight and volume, the downregulation of DNMT1 and CD44 mRNAs, and the highest upregulation of miR-148a-3p." (PMID 37304067, 2023). "The DNA methyltransferase DNMT1 was involved in regulation of DNA methylation to silence tumour suppressor genes." (PMID 36869331, 2023). "There were significant tumor growth delays, decreasing expression of DNMT1 and upregulating expression of p21 by aza-T-dCyd and decitabine treatment in mice bearing xenograft tumors." (PMID 37045940, 2023). "Tumor growth and DNMT1 were significantly inhibited, and p21 was upmodulated in mice bearing HCT116 DNMT1+/+ xenograft and bladder PDX tumors." (PMID 37045940, 2023). "To further explore TEC heterogeneity as relates to Dnmt1 expression and anti-tumor immune responses, we carried out scRNA-seq on FACS-isolated CD45-/CD31+ ECs from collagenase-dispersed, normal mammary glands." (PMID 37055433, 2023). "DNMT1 overexpression and low expression of RNF180 were associated with poor prognosis and aggressive tumor behavior." (PMID 37147733, 2023). "Hypomethylating drug 5-Aza-2’-deoxycytidine (5-Aza-2’) enhances transcription of tumor suppressor genes and induces replication errors via entrapment of DNMT1, yielding DNA-protein crosslinks." (PMID 36792656, 2023). "We also identify a fibroblast growth factor-2 (FGF2) mediated mechanism for DNMT1 regulation, thus linking a potent endothelial cell (EC) mitogen with proliferative yet immunologically anergic tumor vasculature." (PMID 37055433, 2023). "The involvement of DNMT1 in DDR has important implications for therapeutic strategies aimed at targeting DNA methylation in tumor cells." (PMID 37894343, 2023). "Recent evidence has shown that tumor invasion into neighboring tissue is regulated by various methyltransferases, such as DNMT1 and DNMT3B." (PMID 37367043, 2023). "The expression of CAMK2N1 was obviously increased when DNMT1 expression was markedly reduced in tumor tissues." (PMID 36755811, 2023). "STAT3 can also regulate H3K4me3 of its target genes in T cells under Th17 cell-polarizing conditions and recruit DNA methyltransferase 1 (DNMT1) to gene promoters to silence tumor suppressor genes, such as SHP-1, in malignant T lymphocytes." (PMID 36740715, 2023).
tumor (continued). "In conclusion, our study suggests that PMA-induced differentiation of THP-1 cells is promoted by the depletion of UHRF1 or DNMT1 which also reduced in vivo tumor growth." (PMID 37573395, 2023). "Other mi-RNAs, such as miR-152, miR-185, and miR-342, lead to DNA hypomethylation, promoting the expression of tumor-suppressor genes via DNMT1." (PMID 37046597, 2023). "The differential expression of BEX1 in tumor and normal tissues is regulated by DNMT1, which maintains the self-renewal capacity of the hepatocellular carcinoma CSCs by activating the Wnt/β-catenin signaling pathway." (PMID 37394582, 2023). "UHRF1 degradation decreases the recruitment of DNMT1 to chromatin, and decreases the level of genome-wide DNA methylation, thereby elevating the expression of tumor suppressor genes and decreasing cell viability." (PMID 37788997, 2023). "Expression of one of the targets of their hub genes was the maintenance methyltransferase, DNMT1, that was significantly up-regulated consistently in the four stages of tumor progression analyzed." (PMID 37243196, 2023). "As the levels of demethylation in DNMT1+/+ and DNMT1−/− cells were roughly comparable, and we further investigated the implication of DNMT1 in the repression of the tumor suppressors at their associated chromatin in HCT116-DNMT1 model." (PMID 37045940, 2023). "Interference with the expression of DNMT1 restores the expression of certain tumor suppressor genes and suppresses tumor growth." (PMID 36755811, 2023). "Here the authors show that conditional deletion of Dnmt1 in endothelial cells is sufficient to promote T cell infiltration, reduce tumor growth and enhance ICB response in preclinical models." (PMID 37055433, 2023). "Nevertheless, significant inhibition of 22Rv1 tumor xenografts following gDEC treatment aligned with decreased DNMT1." (PMID 37345101, 2023). "The tumor volume and weight in the mice transduced with sh-DNMT1 were reduced in the presence of ADR." (PMID 35255904, 2022). "A recent study showed that inhibiting the expression of DNA methyltransferase 1 can reduce MDSCs and increase tumour-infiltrating T cells to prevent tumour growth in the TME of oral squamous cell carcinoma (OSCC)." (PMID 36405713, 2022). "In return, LINC00173 inhibits the expression of DNMT1, blocking tumour cell proliferation and enhancing the sensitivity to chemotherapy." (PMID 35838271, 2022). "It has been reported that UHRF1 silences tumor suppressor genes through recruiting epigenetic enzymes, including DNA methyltransferase (DNMT1) and histone lysine methyltransferases (G9a and Suv39H1) 10-13." (PMID 35664070, 2022). "In prostate cancer, DNMT1 acts as tumor suppressor in the early stages of tumorigenesis, while contributing to metastasis as an oncogenic factor in the later stage." (PMID 35203421, 2022). "Several DNA5mC regulators were found to be significantly overexpressed in tumor tissues, including DNMT1, DNMT3B, TET2, TET3, MBD1, and SMUG1." (PMID 36425533, 2022). "DNMT1 was almost completely suppressed in tumor cells by zebularine, indicating it has high selectivity toward DNMT1." (PMID 37077808, 2022). "LINC00337 recruits DNMT1 to the promoter of the tumor-suppressive gene, CNN1 (calponin 1), to repress its expression in colorectal cancers, which further promotes VEGF-mediated tumor angiogenesis." (PMID 36010595, 2022). "HBx expression increased total DNMT activity by upregulating DNMT1, DNMT3A1, and DNMT3A2 and selectively promoted the regional hypermethylation of specific tumor suppressor genes, which caused hepatocarcinogenesis." (PMID 36325353, 2022). "A study showed that clofarabine inhibited the proliferation of tumor cells by downregulating DNMT1 and inhibiting the methylation of TSG, such as PTEN, APC, and RARβ2." (PMID 37077808, 2022). "The first CTL observation searches for a state with high expression of DNMT1 and oncogenes leading to tumor invasion." (PMID 35898303, 2022).
tumor (continued). "The second gene in this group, Particl, is involved in the response to irradiation and affords an RNA binding platform for genomic silencers, such as DNA methyltransferase 1 and histone tri-methyltransferases, to reign in the expression of tumor suppressors." (PMID 35267932, 2022). "On the other hand, a recent study found miR-142-5p acting as a tumor suppressor in BC, inhibiting cell invasion and migration by targeting DNMT1." (PMID 35846122, 2022). "Several recent studies have found that LncRNA modulated the stability of DNMT1, leading to the DNA methylation of tumor suppressor genes." (PMID 36527094, 2022). "Aberrant expression/overexpression of DNMT-1 is an important regulator in the progression of human malignancies, acting to induce the silencing of tumor suppressors by mediating methylation of their promoters." (PMID 35401185, 2022). "Regulators with amplificated CNV tended to highly expressed in tumor samples (e.g., DNMT1, ALYREF, and NSUN5), and vice versa (e.g., NSUN7 and NSUN6)." (PMID 36389669, 2022). "In mice, the activity of the combination was accompanied by disruption of the STAT3- DNMT1 complex formation and demethylation of several tumor-suppressor gene promoters." (PMID 35327559, 2022). "We also confirmed that the average tumour weight in the DNMT1 knockdown group was lower than that in the control group." (PMID 36273188, 2022). "Cell signaling studies show that the APC (Adenomatous Polyposis Coli) as a tumor suppressor gene and a regulator of the Wnt signaling pathway through β-catenin stability and/or degradation controls DNMT1 gene expression." (PMID 36147796, 2022). "Increasing evidence has shown that hypermethylation in the 5′–C–phosphate–G–3 (5′-CpG-3′) islands of the promoter region of miRs, functioning as tumor suppressors by DNMT-1, often mediates activation of the proliferation or drug-resistance-related pathways." (PMID 35401185, 2022). "Our results showed that the tumours in the DNMT1 knockdown group were much smaller than those in the control group." (PMID 36273188, 2022). "In lung adenocarcinoma (LUAD), lncRNA HAGLR was identified as a tumor suppressor by recruiting DNMT1 to the promoter of E2F1 to inhibit tumor growth." (PMID 35292092, 2022). "3The CpG islands in the promoter fragment of lncRNA SPRY4-IT1 induce the expression of SPRY4-IT1 by inhibiting the activity of DNA methyltransferase 1 (DNMT1), thereby promoting tumor metastasis." (PMID 35211630, 2022). "In the process of CRC, LINC00114 expression trends to up-regulate, and down-regulating LINC00114 inhibits proliferation in vitro, and retards tumor formation in vivo via reducing EZH2/DNA methyltransferase 1-induced methylation of miR-133b promoter." (PMID 35414117, 2022). "We detected the formed-tumour sizes in the control group and DNMT1 silencing group when the mice were sacrificed 4 weeks later." (PMID 36273188, 2022). "In fact, the MYC oncogene promotes overexpression of DNMT1, which results in tumor maintenance and progression in BL." (PMID 35326620, 2022). "The decreased transcription of DNA methyltransferase 1 (DNMT1) protein results in the increased efficiency of tumor cell antigen synthesis and the inhibition of regulatory T-cell proliferation." (PMID 35530846, 2022). "DNMT1 was highly expressed in the nuclei of tumor cells, while DNMT1 was lowly expressed in adjacent liver cells." (PMID 35092191, 2022). "In B-NHL patients, decitabine decreased tumor DNMT1 and increased tumor apoptosis (p < 0.05), mitoses (p = 0.02), and copper/platinum transporter CTR1." (PMID 35326620, 2022). "DNA methyltransferase 1 (DNMT1) can impair the homing ability of cytotoxic T cells to tumor cells by down-regulating CXCL12." (PMID 34631695, 2021). "To investigate the molecular mechanisms associated with Dnmt1 deletion in ALK transgenic mice, we performed RNA-seq analyses of thymocytes isolated from Ctrl, KO, and ALKKO mice and compared it with our tumor RNA-Seq data." (PMID 33310759, 2021).